TRIM65 (tripartite motif containing 65)
Description:
E3 ubiquitin ligase that plays a role in several processes including innate immnity, autophagy or inflammation. Negatively regulates miRNAs by modulating the ubiquitination and stability of TNRC6A, a protein involved in RNA-mediated gene silencing by both micro-RNAs (miRNAs) and short interfering RNAs. This ubiquitination results in the suppressed expression of miR-138-5p leading to increased autophagy. Upon enteroviral infection, promotes 'Lys-63'-mediated ubiquitination activation of IFIH1/MDA5 leading to innate signaling cascade. Mechanistically, selectively recognizes MDA5 filaments that occur on dsRNAs. Plays also a role in limitation of inflammation through different mechanisms. First, promotes 'Lys-48'-mediated ubiquitination of VCAM1 leading to its degradation and limitation of LPS-induced lung inflammation. In addition, negatively regulates inflammasome activation by promoting 'lys48'-linked ubiquitination of NLRP3 which is critical for the inhibition of NLRP3 inflammasome activation in resting macrophages.
Synonyms: 4732463G12Rik
Tractability: Small molecule: a structure with a bound ligand is known. PROTAC: UniProt records ubiquitination sites on it; ubiquitination databases record sites on it; its protein half-life has been measured.
Gene: Protein-coding gene on chromosome 17 (75,880,335 to 75,897,014, reverse strand). Ensembl gene ENSG00000141569.
Subcellular location: Cytoplasm
Subcellular location (Human Protein Atlas): Cytosol; Nucleoplasm; Vesicles
Gene Ontology:
Molecular function: protein domain specific binding; ubiquitin protein ligase activity; ubiquitin-protein transferase activity; metal ion binding; zinc ion binding
Biological process: antiviral innate immune response; negative regulation of inflammatory response; negative regulation of NLRP3 inflammasome complex assembly; positive regulation of autophagy; positive regulation of interferon-beta production; positive regulation of protein oligomerization; protein K48-linked ubiquitination; protein K63-linked ubiquitination; type I interferon-mediated signaling pathway; protein ubiquitination
Cellular component: cytoplasm; cytosol; nucleoplasm
Genetic constraint (gnomAD): Loss-of-function variants: 47 observed, 27.91 expected, observed/expected ratio (o/e) 1.68, 90% interval 1.32 to 1.95. The synonymous counts are far from expectation, so gnomAD's model fits this gene poorly and the ratio says little. Missense variants: 698 observed, 569.02 expected, observed/expected ratio (o/e) 1.23, 90% interval 1.15 to 1.31. Synonymous variants: 337 observed, 257.64 expected, observed/expected ratio (o/e) 1.31, 90% interval 1.2 to 1.43.
Homologues: Orthologues: chimpanzee TRIM65 (99% identical), macaque TRIM65 (94% identical), dog TRIM65 (76% identical), pig TRIM65 (76% identical), guinea pig TRIM65 (72% identical), mouse Trim65 (65% identical), rat Trim65 (64% identical). Paralogues in human: TRIM47 (28% identical), TRIM11 (23% identical), TRIM72 (21% identical), TRIM58 (21% identical), TRIM25 (20% identical), TRIM4 (20% identical), TRIM69 (20% identical), TRIM39 (20% identical), MID1 (20% identical), TRIM17 (20% identical), TRIM5 (20% identical), TRIM21 (20% identical), and 68 more.
Diseases named in the same sentence as TRIM65 in open-access papers:
TRIM65 is named in the same sentence as 40 diseases in open-access papers, as found by Europe PMC text mining. Sharing a sentence is not in itself a finding about the gene and the disease. The quoted sentences say what the papers report.
glioma (6 papers, 2021 to 2025). A benign or malignant brain and spinal cord tumor that arises from glial cells (astrocytes, oligodendrocytes, ependymal cells). "TRIM65 was originally found to be a genetic polymorphism associated with white matter lesions, and subsequent research found that TRIM65 was abnormally highly expressed in many types of cancer, including lung, liver, bladder, and glioma." (PMID 36035221, 2022). "For example, LINC01857 sponges miR-1281 to promote TRIM65 expression and thus facilitates the development of glioma." (PMID 34425868, 2021). "LINC01857 acts as an oncogene that promotes BC development by promoting H3K27Ac and CREB1 transcription, regulates glioma progression by modulating the miR-1281/TRIM65 pathway, promotes the proliferation of cancer cells by activating the PI3K/mTOR pathway, and facilitates the EMT process in DLBCL." (PMID 36168326, 2022). "Therefore, LINC01857 is believed to promote glioma progression and tumor growth via regulation of the miR-1281/TRIM65 axis." (PMID 36139694, 2022). "TRIM65 mRNA is targeted by miR-1281, and LINC01857 induces TRIM65 expression in gliomas by restraining miR-1281." (PMID 36139694, 2022).
lung cancer (6 papers, 2019 to 2024). A malignant neoplasm involving the lung. "And knockdown of TRIM65 suppressed survival of DDP-resistant lung cancer cell lines and tumor growth." (PMID 36654781, 2023). "TRIM65 is a well-known cancer biomarker and a potential therapeutic target for colorectal cancer and lung cancer treatment." (PMID 36402840, 2022). "TRIM65 is overexpressed in lung cancer tissues and may act as an oncogene in lung cancer by promoting lung cancer proliferation, migration, and invasion." (PMID 31160576, 2019).
colorectal cancer (5 papers, 2019 to 2022). A primary or metastatic malignant neoplasm that affects the colon or rectum. "Here, we found that TRIM65 is upregulated and associated with poor survival in colorectal cancer (CRC)." (PMID 31332286, 2019). "TRIM65 has also been shown to promote colorectal cancer metastasis through targeted ubiquitination and degradation of ARHGAP35 protein and activates ERK1/2/C-myc signaling by targeting ubiquitination to degrade DUSP6 protein, thereby promoting the invasion of endometrial stromal cells." (PMID 36035221, 2022). "TRIM65 accelerates colorectal cancer metastasis by targeted degradation of ARHGAP35 protein, promotes the invasion of endometrial stromal cells through DUSP6 ubiquitination, activates ERK1/2/C-myc signals, and promotes bladder cancer cells through ubiquitination and degradation of ANXA2 invasion." (PMID 36035221, 2022). "In addition, an E3 ubiquitin ligase, tripartite motif-containing protein 65 (TRIM65), has been found to modulate the migration and metastasis of colorectal cancer cells." (PMID 33014840, 2020).
hepatocellular carcinoma (4 papers, 2018 to 2024). A malignant tumor that arises from hepatocytes. "TRIM65 acts as an oncogene in hepatocellular carcinoma, and its high expression promotes cancer cell proliferation and metastasis in liver cancer tissue." (PMID 36035221, 2022). "TRIM65, an E3 ligase, is O‐GlcNAcylated and highly expressed in hepatocellular carcinoma (HCC)." (PMID 39005234, 2024).
urothelial carcinoma of the bladder (4 papers, 2020 to 2025). "Among them, tripartite motif containing 65 (TRIM65) was reported to ubiquitylate ANXA2 in urothelial carcinoma of the bladder (UCB)." (PMID 38688909, 2024). "A previous study reported that TRIM65 promoted bladder urothelial carcinoma progress via ubiquitination of ANXA2." (PMID 35977942, 2022).
viral infections (4 papers, 2021 to 2022). "TRIM65 belongs to the ubiquitin E3 ligase family and plays an important role in developmental disorders, viral infections, and cancer." (PMID 36035221, 2022). "Both FBXO21 and TRIM65 are necessary for the production of type I IFNs in response to viral infection." (PMID 33956915, 2021).
bladder cancer (3 papers, 2022 to 2025). "Fourteen TRIM family proteins were associated with bladder cancer (tumor-promoting: TRIM9, TRIM25, TRIM26, TRIM28, TRIM29, TRIM59, TRIM65, and TRIM66; tumor-suppressive: TRIM19 and TRIM38)." (PMID 40723250, 2025). "Studies have shown that TRIM65 is a potential carcinogen in the pathogenesis of bladder cancer, and TRIM65 overexpression is an independent prognostic factor for bladder cancer." (PMID 36035221, 2022). "Other TRIM proteins (TRIM9, TRIM38, TRIM65, and TRIM66) promoted progression of bladder cancer by targeting GLUT1, ANXA2, and MMP11." (PMID 40723250, 2025).
breast carcinoma (3 papers, 2022 to 2024). "Although TRIM65 also has a large proportion of amplification, prognosis analysis shows that there is no significantly correlation between TRIM65 overexpression and prognosis of breast cancer." (PMID 36906594, 2023). "However, there are no reports on the differential expression of TRIM65 in breast cancer." (PMID 36035221, 2022).
cervical cancer (3 papers, 2022 to 2024). A primary or metastatic malignant neoplasm involving the cervix. "Since HPV status of cervical cancer is extensively connected with the immune landscape, we intend to explore the role and mechanism of TRIM65 in HPV-associated cervical cancer." (PMID 35402260, 2022). "Tripartite motif containing 65 (TRIM65) is an E3 ubiquitin ligase that has been implicated in a variety of cellular processes as well as tumor progression, but its biological role and the underlying mechanism in cervical cancer is unclear." (PMID 35402260, 2022). "However, the effect and underlying mechanism of TRIM65 E3 ligase on cervical cancer carcinogenesis remains unclear." (PMID 35402260, 2022). "However, it is still unclear whether the inhibitory effect of TRIM65 knockdown on cervical cancer is associated with apoptosis and cell cycle." (PMID 35402260, 2022). "TRIM65 expression was significantly higher in cervical cancer tissues than that in adjacent normal cervical tissues from the First Affiliated Hospital of Nanchang University." (PMID 35402260, 2022). "Collectively, these data suggested that the TRIM65 knockdown significantly activated autophagy and promoted apoptosis, resulting in the increase of cervical cancer cell death." (PMID 35402260, 2022). "Further experiments indicated that TRIM65 knockdown increased autophagic flux by accelerating degradation of autolysosome which is essential for inhibition of cervical cancer." (PMID 35402260, 2022). "TRIM65 knockdown exhibits anti-proliferative activity by both activating autophagy and apoptosis in cervical cancer." (PMID 35402260, 2022). "We provided strong evidence that TRIM65 knockdown remarkably restrained the proliferation and migration of cervical cancer cell, while the pro-tumor activity was observed in the cells with TRIM65 overexpression." (PMID 35402260, 2022). "All these results indicated that TRIM65 functioned as an oncogene that promoted the growth and migration of the cervical cancer cells in vitro." (PMID 35402260, 2022). "In the present study, we demonstrated for the first time that TRIM65 was closely related to carcinogenesis of cervical cancer." (PMID 35402260, 2022). "Autophagy is an important and evolutionarily conserved mechanism for maintaining cellular homeostasis, which has been shown to play a key role in TRIM65-induced cervical cancer cell proliferation from our data." (PMID 35402260, 2022). "Thus, the interactions and molecular mechanisms between autophagy and apoptosis are worth to be further explored in cervical cancer cells with TRIM65 depletion." (PMID 35402260, 2022). "Taken together, our studies demonstrated that TRIM65 knockdown promotes cervical cancer cell death through enhancing autophagy and apoptosis, suggesting that TRIM65 may be a potential therapeutic target for cervical cancer clinically." (PMID 35402260, 2022). "Therefore, to clarify if there was an intrinsic link between autophagy and apoptosis induced by TRIM65 knockdown, we examined the apoptotic effect of TRIM65 siRNA on cervical cancer cells treated with autophagy inhibitor CQ." (PMID 35402260, 2022).
cervical cancer (continued). "Since HPV is the most important factor for pathogenesis of cervical cancer and autophagy plays a key role in defending the infection of the virus in cervical carcinogenesis, we examined whether TRIM65 regulated autophagic flux." (PMID 35402260, 2022). "For survival analysis, the patients with cervical cancer from TCGA’s cervical carcinoma data set were divided into a high expression group and a low expression group based on median expression level of TRIM65 and the Kaplan-Meier method was applied to plot overall and disease-free survival curves." (PMID 35402260, 2022). "Furthermore, we investigated whether TRIM65 knockdown-mediated the inhibition of cervical cancer cell proliferation was the consequence of increased autophagic flux." (PMID 35402260, 2022). "The results showed that the patients with low TRIM65 expression were tendentiously associated with longer survival time or disease-free survival time although there were no significant statistical differences, suggesting that TRIM65 may be involved in carcinogenesis of human cervical cancer." (PMID 35402260, 2022). "Our results showed that TRIM65, as an E3 ubiquitin ligase, did not directly degrade autophagy-related proteins in cervical cancer, suggesting that it may target an upstream co-regulator of autophagy and apoptosis." (PMID 35402260, 2022). "In addition, we observed that TRIM65 knockdown promoted autophagy-related apoptosis of cervical cancer cells, but did not affect the cell cycle." (PMID 35402260, 2022).
gastric cancer (3 papers, 2022 to 2024). A primary or metastatic malignant neoplasm involving the stomach. "The suppression of PPM1A counteracted the inhibitory effects of TRIM65 knockdown on cancer progression, suggesting that TRIM65 facilitates gastric cancer progression by degrading PPM1A." (PMID 39768197, 2024). "In gastric cancer, TRIM65 expression was elevated in both clinical tumor tissues and cell lines." (PMID 39768197, 2024). "TRIM65 knockdown inhibits autophagy of A549/DDP cells through the miR-138-5P/ATG7 pathway, whereas TRIM14 promotes autophagy in gastric cancer cells by activating the AMPK pathway." (PMID 36587218, 2022).
liver cancer (3 papers, 2019 to 2024). An epithelial or non-epithelial malignant neoplasm that arises from the liver. "A pan‐cancer analysis based on multiple cancer tissue microarray showed that TRIM65 was selectively overexpressed in liver cancer and we validated the up‐regulation of TRIM65 using the HCC tissue microarray and frozen tissues specimens." (PMID 39005234, 2024).
Stroke (3 papers, 2016 to 2019). Sudden impairment of blood flow to a part of the brain due to occlusion or rupture of an artery to the brain. "Other single nucleotide polymorphisms including rs7214628 in TRIM65 and rs78857879 in EFEMP1 had also been verified at genome-wide significance level by one later genome-wide meta-analysis study in overall combined community populations with stroke patients of European ancestry." (PMID 31396257, 2019).
renal carcinoma (2 papers, 2024 to 2025). A carcinoma arising from the epithelium of the renal parenchyma or the renal pelvis. "In renal cancer cells, the expression of the E3 ligase Trim65 is elevated, and overexpression of Trim65 promotes the growth of renal cancer cells." (PMID 40225869, 2025). "Overexpression of TRIM65 significantly increased the proliferation of renal cancer cells, as well as the RCC cell growth both in low serum medium and full growth medium." (PMID 38777825, 2024). "Our findings proved that downregulation of TRIM65 can markedly suppress renal cancer cell proliferation as well as anchorage-independent growth, which was consistent with TRIM65 overexpression data." (PMID 38777825, 2024). "To explore the role of TRIM65 in RCC, we first analyzed the mRNA expression of TRIM65 in renal cancer patients from the TCGA database via the UALCAN portal." (PMID 38777825, 2024). "Results of western blotting showed that all renal cancer cells had significantly raised levels of TRIM65 protein." (PMID 38777825, 2024). "We first detected the cell cycle through flow cytometry, after confirming that TRIM65 has a regulatory effect on the renal cancer cell cycle, we also conducted a preliminary exploration of the existing key factors in our research group." (PMID 38777825, 2024). "Moreover, upregulation of TRIM65 promoted the colony formation and anchorage-independent growth of renal cancer cells, which were consistent with the results of TRIM65 knockdown." (PMID 38777825, 2024). "Furthermore, we found that ectopic overexpression of BTG3 eliminated the acceleration of TRIM65 on the anchorage-independent growth abilities of renal cancer cells in soft agar assays." (PMID 38777825, 2024). "Furthermore, we found that knockdown of TRIM65 obviously weakened the anchorage-independent growth abilities of renal cancer cells through soft agar assays." (PMID 38777825, 2024).
renal cell carcinoma (2 papers, 2024 to 2025). "It is also noteworthy that our findings indicate that TRIM65 plays a role in the development of renal cell carcinoma by regulating BTG3 and the cell cycle." (PMID 40264575, 2025). "However, the role of TRIM65 in renal cell carcinoma (RCC) and the underlying mechanism has not been determined yet." (PMID 38777825, 2024).
renal fibrosis (2 papers, 2025 to 2026). A final common manifestation of a wide variety of chronic kidney diseases characterized by glomerulosclerosis and tubulointerstitial fibrosis. "Most recently, we also demonstrated that TRIM65 deficiency alleviates renal fibrosis through NUDT21‐mediated alternative polyadenylation." (PMID 40264575, 2025). "Moreover, the TRIM65 protein plays a role in the regulation of renal fibrosis by targeting the NUDT21‐mediated selective polyadenylation pathway." (PMID 40264575, 2025).
acute kidney injury (1 paper, 2025). Sudden and sustained deterioration of the kidney function characterized by decreased glomerular filtration rate, increased serum creatinine or oliguria. "In the context of acute kidney injury (AKI) resulting from a multiplicity of causes, including chemotherapeutic agents such as cisplatin, I/R injury, and rhabdomyosarcoma, the TRIM65 protein is upregulated in renal tubular epithelial cells." (PMID 40264575, 2025). "In the absence of TRIM65, VDAC1 is maintained at a lower level of protein through the autophagy pathway, which promotes the repair of mitochondrial function and ultimately protects against acute kidney injury." (PMID 40264575, 2025).